NME1 (NME/NM23 nucleoside diphosphate kinase 1)
Description:
Catalyzes the transfer of a gamma-phosphoryl group from a nucleoside triphosphate, mainly ATP, to a nucleoside diphosphate via a ping-pong mechanism involving a phosphohistidine intermediate, therefore contributing to the nucleoside triphosphate homeostasis. Also phosphorylates geranyl pyrophosphate (GPP) and farnesyl pyrophosphate (FPP), linking it to isoprenoid metabolism. Additionally, functions as a non-specific serine/threonine kinase and histidine protein kinase, transferring phosphoryl groups from its active site to target proteins. May function as a Mg(2+)-dependent single-stranded DNA endonuclease as part of the SET complex, cooperating with the 3'-5' exonuclease TREX1 to mediate apoptotic DNA fragmentation in cytotoxic T lymphocytes. Reported to nick one DNA strand, enabling TREX1 to remove nucleotides from the free 3' end, enhancing DNA damage and suppressing DNA end reannealing and repair. Has been shown to cleave double strands DNA within the 3'-portions of both 5'-SHS silencer and NHE basal promoter element of the PDGFA gene, potentially repressing its transcription. May also function as a Mg(2+)-dependent 3'-5' DNA exonuclease, excising nucleotides from 3' single-stranded DNA or DNA with 3' single strand overhangs, suggesting a role in DNA nucleolytic processing. Involved in the regulation of tumor metastasis and cellular differentiation (By similarity). Also required for cell motility. May control, with NME2, AcCoA usage between histone acetylation and fatty acid synthesis, possibly by binding and releasing AcCoA at transcriptionally active chromatin regions in proximity to histone acetyltransferase (HAT) (By similarity).
Synonyms: NDPK A; NDK1; GAAD; NDPKA; NM23; NM23-H1; AWD; NB; NBS; NDKA; NDPK-A
Tractability: Small molecule: a structure with a bound ligand is known; it has a binding pocket of medium quality. PROTAC: UniProt records ubiquitination sites on it; ubiquitination databases record sites on it; its protein half-life has been measured.
Target class: Enzyme; Transferase
Gene: Protein-coding gene on chromosome 17 (51,152,949 to 51,162,428, forward strand). Ensembl gene ENSG00000239672.
Subcellular location: Cytoplasm; Nucleus; Cell membrane
Subcellular location (Human Protein Atlas): Cytosol
Pathways (Reactome):
Drug ADME: Azathioprine ADME; Ribavirin ADME
Metabolism: Interconversion of nucleotide di- and triphosphates
Gene Ontology:
Molecular function: 3'-5'-DNA exonuclease activity; ADP binding; DNA binding; DNA endonuclease activity; DNA nuclease activity; farnesyl diphosphate kinase activity; GDP binding; identical protein binding; kinase activity; magnesium ion binding; nucleoside diphosphate kinase activity; phosphotransferase activity, phosphate group as acceptor; protein binding; protein histidine kinase activity; protein serine kinase activity; ribosomal small subunit binding; RNA binding; acetyl-CoA binding; coenzyme A binding; succinyl-CoA binding; protein serine/threonine kinase activity
Biological process: apoptotic DNA fragmentation; DNA catabolic process; isoprenoid metabolic process; ITP biosynthetic process; nucleoside diphosphate metabolic process; nucleoside triphosphate biosynthetic process; positive regulation of epithelial cell proliferation; protein hexamerization; acetyl-CoA catabolic process; base-excision repair; granzyme-mediated apoptotic signaling pathway; negative regulation of cell population proliferation; regulation of apoptotic process; regulation of fatty acid biosynthetic process; CTP biosynthetic process; GTP biosynthetic process; nucleoside phosphate metabolic process; purine-containing compound metabolic process; UTP biosynthetic process
Cellular component: cytoplasm; cytosol; early endosome; extracellular exosome; membrane; nucleus; ruffle membrane; chromatin; endoplasmic reticulum; plasma membrane
Genetic constraint (gnomAD): Loss-of-function variants: 8 observed, 15.88 expected, observed/expected ratio (o/e) 0.5, 90% interval 0.29 to 0.91. The upper end of that interval is the gene's LOEUF score, 0.91, which puts it in group 3 of 6, group 1 being the genes least tolerant of losing a copy. Missense variants: 163 observed, 204.72 expected, observed/expected ratio (o/e) 0.8, 90% interval 0.7 to 0.91. Synonymous variants: 69 observed, 71.99 expected, observed/expected ratio (o/e) 0.96, 90% interval 0.79 to 1.17.
Homologues: Orthologues: rat Nme1 (95% identical), pig NME1 (95% identical), mouse Nme1 (94% identical), guinea pig NME1 (92% identical), rabbit NME1 (92% identical), dog NME2 (88% identical), zebrafish nme2b.1 (84% identical), zebrafish nme2b.2 (78% identical). Paralogues in human: NME2 (87% identical), NME3 (66% identical), NME4 (56% identical), NME7 (32% identical), NME5 (30% identical), NME6 (28% identical), NME8 (27% identical), NME9 (12% identical).
Diseases named in the same sentence as NME1 in open-access papers:
NME1 is named in the same sentence as 133 diseases in open-access papers, as found by Europe PMC text mining. Sharing a sentence is not in itself a finding about the gene and the disease. The quoted sentences say what the papers report.
breast carcinoma (96 papers, 1993 to 2026). "Increased NME1 expression in primary breast tumors is also associated with a worse prognosis in breast cancer." (PMID 34741115, 2021). "NME1 EcoR1 (rs34214448) polymorphism has a statistically significant association with breast cancer risk (P < 0.001)." (PMID 32462300, 2020). "Whereas reduced expression of NME1 is associated with a high potential for metastasis in some tumour types, like breast cancer and melanoma, its expression is increased in aggressive NBTs." (PMID 18700951, 2008). "Thus, loss of NME1 in breast carcinoma cells is a key emerging feature of the in situ-to-invasive breast carcinoma transition." (PMID 34012098, 2021). "Similarly, NME1 histidine kinase activity was associated with the motility suppressive activity of NME1 in breast carcinoma." (PMID 32823988, 2020). "Thus, we propose NME1 as a potential marker to predict in situ tumors with high risk to progress into invasive breast carcinomatous lesions, which remains a critical issue in breast cancer management." (PMID 34012098, 2021). "Finally, we found a specific association of NME1 with endocytic clathrin-coated structures and a regulation of MT1-MMP surface levels by dynamin downstream of NME1, clarifying the mechanism underlying the increased invasive potential of breast cancer cells during the DCIS-to-IBC transition." (PMID 34012098, 2021). "For example, the HSP90AA1 gene stabilizes the NME1 protein in breast cancer cells, and its overexpression protects endogenous NME1 protein from degradation, leading to reduced metastasis formation in vitro and in vivo." (PMID 41507145, 2026). "Similar to our research findings, a previous study has indicated that HSP90AA1 interacts with NME1 and increases NME1 lifetime by impeding its ubiquitin-proteasome-mediated degradation and suppresses breast cancer metastasis." (PMID 41507145, 2026). "Functionally, NME1 has been characterized as a metastasis suppressor in both melanoma and breast cancer, where NME1 expression levels directly correlate with its ability to suppress cell migration." (PMID 40835738, 2025). "Increased LCFA-CoA in the MDA-MB-231 breast cancer cell model inhibited NME1/2’s NDPK activity and resulted in endocytosis inhibition." (PMID 39063217, 2024). "NME1 overexpression in breast carcinoma cells can promote KSR phosphorylation and decrease MAPK activation." (PMID 39063217, 2024). "Most of the studies demonstrate that high NME1 RNA and protein levels are correlated with a good prognosis in cancer, including breast cancer, ovarian cancer, cervical cancer, head and neck carcinoma, and melanoma." (PMID 39063217, 2024). "Recently, it was shown that in patients with breast carcinoma, NME1 is also secreted into the serum." (PMID 36010906, 2022). "Next, we intended to investigate the effect of NME1/2-containing EVs derived from breast carcinoma cells on fibroblasts, which are representative cells of the tumour microenvironment." (PMID 36010906, 2022). "We first performed a detailed subtype-specific analysis of breast carcinoma cell-derived EVs, which showed that NME1 was only present in mEVs." (PMID 36010906, 2022). "In this study, we used human breast carcinoma cells and skin-derived fibroblasts as models to examine the role of EV-derived NME1/2 exerted on the microenvironment." (PMID 36010906, 2022). "Next, we treated normal skin fibroblasts by a mixture of microvesicles and small EVs from NME1 or NME2 overexpressing breast carcinoma cells and then examined their effect on the RNA pool of fibroblasts." (PMID 36010906, 2022). "On the other hand, ionizing radiation inhibited the expression of NME1, a metastasis suppressor in breast cancer cells, and this inhibitory effect was counteracted by melatonin." (PMID 35625825, 2022). "Our study here showed that LCFA-CoA, by inhibiting NME1, contributes to breast cancer metastasis in mice exposed to an HFD." (PMID 35259022, 2022).
breast carcinoma (continued). "Functional experiments showed that the enforced expression of LINC00261 suppressed the EMT development in breast cancer cells by enhancing NME/NM23 nucleoside diphosphate kinase 1 (NME1) mRNA stability." (PMID 36613528, 2022). "In a Boyden chamber migration assay, both WT and R58E mutant NME1 expression significantly suppressed cell migration under serum-starved conditions in multiple breast cancer cell lines." (PMID 35259022, 2022). "This study identifies the down-modulation of NME1 as a potent driver of the in situ-to invasive transition during breast cancer progression." (PMID 34012098, 2021). "Collectively, these findings indicate that down-regulation of NME1 NDPK correlates with the onset of breast cancer invasion." (PMID 34012098, 2021). "All together, our data uncovered a biphasic NME1 alteration in breast cancer with a characteristic up-regulation in DCIS lesions and a robust down-modulation at the onset of the invasive switch and in invasive lesions." (PMID 34012098, 2021). "Collectively, these data indicate that MT1-MMP mediates both an increase in invasion and collagenolysis in breast cancer cells with reduced NME1 activity." (PMID 34012098, 2021). "At this stage, information regarding the relative expression of NME1 and NME2 and stoichiometry of NME1/NME2 hetero-hexamers in different breast cancer cells is missing." (PMID 34012098, 2021). "Using this system, they find that OXPHOS inhibition attenuates the lung metastatic capacity of breast cancer cells and that overexpression of the metabolic enzyme NME1 increases lung metastasis." (PMID 34741115, 2021). "To test this, we stably overexpressed NME1 in two highly invasive and metastatic human breast carcinoma cell lines, MDA-MB-435 and MDA-MB-231T, to determine its effects on the EMT phenotype." (PMID 33918324, 2021). "Recent data showed that dynamin 2 oligomerization is promoted by NDPK-A/NME1 in breast cancer cells." (PMID 32384736, 2020). "In breast cancer cell lines, NME1 interacts with h-Prune, as is the case in the fruit fly Drosophila melanogaster." (PMID 32823988, 2020). "The expression level of NME1 was found to be inversely proportional to the metastasis potential of several cancers, including breast cancer, gastric cancer, melanoma and colon adenocarcinoma." (PMID 32795291, 2020). "An inverse relationship between metastatic potential and NME1 expression has been reported in several types of cancers, including non-small cell lung cancer, melanoma, breast cancer, hepatocellular carcinoma, gastric cancer, and colorectal cancer." (PMID 32977620, 2020). "In conclusion, PA63 serves for the transport of the tumor metastasis suppressor NDPK-A/NME1 into the cytosol of human breast cancer cells In Vitro, which reduced the migratory activity of these cells." (PMID 32384736, 2020). "More importantly, elevated expression of NME1 has a better prognosis outcome in patients with breast cancer and melanoma." (PMID 32795291, 2020). "Cisplatin increases interstrand DNA cross-links and inhibits pulmonary metastatic colonization in NME1-transfected breast cancer cells." (PMID 32977620, 2020). "We show that Star-PAP and PIPKIα together regulate 3′-end processing and expression of pre-mRNAs encoding key anti-invasive factors (KISS1R, CDH1, NME1, CDH13, FEZ1, and WIF1) in breast cancer." (PMID 29203642, 2018). "The association of plakoglobin with the NME1 promoter is novel and consistent with a previous report that showed decreased Nm23-H1 mRNA levels following plakoglobin knockdown in breast cancer cells." (PMID 24260116, 2013). "NME1, a metastasis-suppressor gene, shows reduced expression in highly metastatic breast cancer cells and was downregulated in cervical cancer LN metastases in this study." (PMID 17242701, 2007).
breast carcinoma (continued). "Its geranyl and farnesyl pyrophosphate activity has been reported with the phosphorylation of geranyl and farnesyl pyrophosphate by purified NME1 from rat and transfected human breast carcinoma cell lines extracts to give product to geranyl and farnesyl triphosphates." (PMID 39063217, 2024). "Overexpression of NME1 leads to the decreased invasive activity of breast cancer cells." (PMID 37681919, 2023). "Thus, our data together support a model that NME1 inhibition by LCFA-CoA is important for the metastasis of breast cancer exposed to oleic acid in vitro or an HFD in vivo." (PMID 35259022, 2022). "In this regard, NME1 expression in breast cancer as well as other carcinomas might be used as a prognostic factor for monitoring progression to invasive states." (PMID 34012098, 2021). "Moreover, NME1 has been shown to regulate global gene expression profiles in breast carcinoma cell lines with the lysophosphatidic acid receptor EDG2 identified as a motility-driving target of NME1-mediated tumor suppression." (PMID 33917317, 2021). "Although the role of CTCF and EGR1 in breast cancer cell proliferation are more well-established as compared to their functions in metastasis, this study supports metastasis suppressor roles for CTCF and EGR1 in breast cancer by acting as positive regulators of NME1 transcription." (PMID 33436746, 2021). "Therefore, we investigated the impact of genetically modified NME1 levels on the rate of MT1-MMP internalization in human breast cancer cell lines." (PMID 34012098, 2021). "Moreover, NME1-dependent genes have a prognostic value as they predicted survival in breast cancer patients." (PMID 34885208, 2021). "The most downregulated gene NME1, a well-known metastasis suppressor gene, was shown to regulate expression of genes important for distant disease-free survival and overall survival in melanoma and breast cancer." (PMID 26759169, 2016). "Moreover, when compared to the MCF10A normal-like cell line, the MCF10DCIS.com human breast carcinoma cell line had 1.4-fold more NME1 protein, whereas the mesenchymal-type MDA-MB-231 human breast tumor cell line had 8-fold less NME1 protein when compared to MCF10DCIS.com cells." (PMID 33918324, 2021). "Finally, we demonstrate a new role for the metabolic enzyme NME1 in promoting breast cancer metastasis, providing proof-of-principle that our culture-transplant system can be used for authentic propagation and engineering of patient tumor cells for functional studies of metastasis." (PMID 34741115, 2021). "As the loss of NME1 may be a prerequisite for the induction of invasive features in patients with DCIS, we anticipate that its clinical management may prevent or delay the invasive switch of breast cancers." (PMID 34012098, 2021). "Additionally, NME1 regulates gene expression in breast cancer cells." (PMID 34885208, 2021). "Similarly, in breast carcinoma cells NME1 overexpression attenuates activation of ERK." (PMID 32823988, 2020). "In addition, LCFA-CoA can directly inhibit the metastasis suppressor gene NME1, weakening its ability to regulate epithelial-mesenchymal transition (EMT) and stromal protein hydrolysis, thus accelerating the metastasis of high-fat diet-associated breast cancer." (PMID 40960294, 2025). "In a study using transfected HEK293T cells and MDA-MB-435 breast carcinoma cells, HPLC of phosphorylated KSR tryptic peptides and site-directed mutagenesis revealed that Ser392 is phosphorylated by NME1." (PMID 39063217, 2024). "Collectively, these data indicate that NME1 controls the endocytic clearance and surface exposure of MT1-MMP in human breast cancer." (PMID 37353690, 2023). "Next, we aimed to understand how extracellular vesicular NME1 and NME2 released by breast cancer cells influence the tumour microenvironment." (PMID 36010906, 2022).